FBXO2 (F-box protein 2)
Description:
Substrate recognition component of a SCF (SKP1-CUL1-F-box protein) E3 ubiquitin-protein ligase complex that mediates the ubiquitination and subsequent proteasomal degradation of target proteins. Involved in the endoplasmic reticulum-associated degradation pathway (ERAD) for misfolded lumenal proteins by recognizing and binding sugar chains on unfolded glycoproteins that are retrotranslocated into the cytosol and promoting their ubiquitination and subsequent degradation. Prevents formation of cytosolic aggregates of unfolded glycoproteins that have been retrotranslocated into the cytosol. Able to recognize and bind denatured glycoproteins, preferentially those of the high-mannose type (By similarity).
Synonyms: FBX2; Nfb42; Fbs1; Fbg1; OCP1
Tractability: Antibody: UniProt places it where antibodies can reach, with medium confidence. PROTAC: its protein half-life has been measured.
Gene: Protein-coding gene on chromosome 1 (11,637,018 to 11,655,785, reverse strand). Ensembl gene ENSG00000116661.
Subcellular location: Cytoplasm; Microsome membrane
Subcellular location (Human Protein Atlas): Cytosol; Nucleoplasm
Pathways (Reactome):
Immune System: Antigen processing: Ubiquitination & Proteasome degradation
Metabolism of proteins: Neddylation
Gene Ontology:
Molecular function: protein binding; ubiquitin protein ligase activity; ubiquitin-protein transferase activity; amyloid-beta binding; carbohydrate binding
Biological process: ERAD pathway; glycoprotein catabolic process; protein modification process; protein ubiquitination; proteolysis; regulation of xenophagy; SCF-dependent proteasomal ubiquitin-dependent protein catabolic process; regulation of protein catabolic process at postsynapse, modulating synaptic transmission
Cellular component: cytoplasm; cytosol; SCF ubiquitin ligase complex; dendritic spine; glutamatergic synapse
Genetic constraint (gnomAD): Loss-of-function variants: 32 observed, 31.28 expected, observed/expected ratio (o/e) 1.02, 90% interval 0.77 to 1.37. The upper end of that interval is the gene's LOEUF score, 1.37, which puts it in group 5 of 6, group 1 being the genes least tolerant of losing a copy. Missense variants: 450 observed, 377.02 expected, observed/expected ratio (o/e) 1.19, 90% interval 1.1 to 1.29. Synonymous variants: 189 observed, 155.24 expected, observed/expected ratio (o/e) 1.22, 90% interval 1.08 to 1.37.
Homologues: Orthologues: chimpanzee FBXO2 (99% identical), macaque FBXO2 (96% identical), dog FBXO2 (90% identical), mouse Fbxo2 (88% identical), pig FBXO2 (88% identical), rat Fbxo2 (88% identical), guinea pig FBXO2 (87% identical), tropical clawed frog fbxo2 (48% identical), zebrafish fbxo2 (33% identical). Paralogues in human: FBXO6 (43% identical), FBXO44 (42% identical), FBXO27 (36% identical), FBXO17 (33% identical), NCCRP1 (26% identical).
Diseases named in the same sentence as FBXO2 in open-access papers:
FBXO2 is named in the same sentence as 42 diseases in open-access papers, as found by Europe PMC text mining. Sharing a sentence is not in itself a finding about the gene and the disease. The quoted sentences say what the papers report.
gastric cancer (5 papers, 2018 to 2023). A primary or metastatic malignant neoplasm involving the stomach. "FBXO2 promoted the proliferation and migration of cancer cells, and FBXO2 knockdown inhibited the proliferation and migration of gastric cancer cells." (PMID 37033662, 2023). "Downregulation of FBXO2 decreased EMT in gastric cancer cells, increased E-cadherin expression, and decreased N-cadherin and vimentin expression." (PMID 37033662, 2023). "Previous study literature has indicated that high expression of FBXO2 promotes the proliferation and migration of gastric cancer cells and which is related to shorter OS of patients." (PMID 33622332, 2021). "FBXO2 regulated the epithelial-mesenchymal transition (EMT) in human gastric cancer cells, suggesting FBXO2 plays an oncogene role in gastric cancer." (PMID 32549792, 2020). "FBXO2 may be a novel clinical target for gastric cancer because low FBXO2 expression can increase the mRNA levels of E-cadherin but reduce the expression of N-cadherin in gastric cancer cell." (PMID 33622332, 2021). "Thus, targeting FBXO2 may be a potent therapeutic strategy for gastric cancer patients with higher expression of FBXO2." (PMID 30999935, 2019). "We demonstrate that EBV infection stimulates FBXO2 expression in NPC cells, however the scenario did not happen in the BL cell lines and gastric carcinoma cell line AGS, the underlying mechanism of FBXO2 regulation by EBV is still elusive." (PMID 30052682, 2018).
hepatocellular carcinoma (3 papers, 2015 to 2025). A malignant tumor that arises from hepatocytes. "Notably, FBXO2 protein levels were substantially upregulated in patients with liver cancer, and FBXO2-mediated KPTN ubiquitination facilitated the progression of hepatocellular carcinoma (HCC)." (PMID 41401028, 2025).
osteosarcoma (3 papers, 2020 to 2025). A usually aggressive malignant bone-forming mesenchymal neoplasm, predominantly affecting adolescents and young adults. "Furthermore, it has been noted that FBXO2 controls the signal transducer and activator of transcription 3 (STAT3) signaling pathway, which is essential for the growth of osteosarcoma cells." (PMID 41035649, 2025). "The other study shows FBXO2 is significantly up-regulated in osteosarcoma, which may modulate STAT3 signaling to regulate proliferation and tumorigenicity of osteosarcoma cells." (PMID 33622332, 2021).
ovarian carcinoma (3 papers, 2022 to 2025). A malignant neoplasm originating from the surface ovarian epithelium. "Manipulation of the expression of FBXO2 affecting ovarian cancer cell proliferation, migration/invasion in vitro, and tumor growth in mice in vivo." (PMID 35525855, 2022). "By integrating the Cancer Genome Atlas (TCGA), Gene Expression Omnibus (GEO), and the Encyclopedia of Cancer Cell Lines (CCLE) databases, we revealed that FBXO2 was selectively highly expressed in ovarian cancer (OV) tissues and cells." (PMID 35525855, 2022). "Through up-regulating FBXO2, SOX6 would promote ovarian cancer progression by inhibiting cell apoptosis." (PMID 40866912, 2025).
cognitive decline (2 papers, 2023 to 2025). "Consistently, transcriptomic studies have revealed Fbxo2 as a gene associated with cognitive decline in AD14,38." (PMID 36609445, 2023). "In contrast, Rapid Decline showed increased β-amyloid (bA), glial and inflammatory markers (CD44, PLXNB1), and stress- and mitochondrial-related proteins (GSTP1, AK4, HSPB2, FBXO2, IGFBP5), which have been associated with neurodegeneration and cognitive decline in AD." (PMID 40799531, 2025).
colorectal cancer (2 papers, 2019 to 2025). A primary or metastatic malignant neoplasm that affects the colon or rectum. "In addition to NCL, FBXO2, which is highly expressed in various human colorectal cancer cell lines, also specifically binds to the GTM-grafted Vγ4δ1-Fc fusion protein in BLI, suggesting a potential ectopic protein ligand for the Vδ1 TCR for which further validation is needed." (PMID 39939816, 2025).
endometrial cancer (2 papers, 2020 to 2025). Primary or metastatic malignant neoplasm involving the endometrium (mucous membrane that lines the endometrial cavity). "By controlling the autophagy signaling system and cell cycle and functioning as an E3 ligase that ubiquitin-dependently degrades Fibrillin-1 (FBN1), FBXO2 has been shown to stimulate the growth of endometrial cancer." (PMID 41035649, 2025). "Consistent with our data, FBXO2 mRNA was increased in the TCGA database that consisted of 552 patients with endometrial cancer." (PMID 32984335, 2020). "Our results suggested that high expression of FBXO2 in EC samples was correlated with endometrial cancer progression." (PMID 32984335, 2020). "In this study, we found that F-box only protein 2 (FBXO2) was up-regulated in 21 endometrial carcinoma (EC) samples compared with five normal endometrium samples based on our Fudan cohort RNA-sequencing." (PMID 32984335, 2020).
Parkinson disease (2 papers, 2020). A progressive degenerative disorder of the central nervous system characterized by loss of dopamine producing neurons in the substantia nigra and the presence of Lewy bodies in the substantia nigra and locus coeruleus. "FBXO2 has been implicated in familial forms of Parkinson’s disease." (PMID 32265286, 2020). "Furthermore, the FBXO2 variant rs99614 C allele was found to decrease the risk for Parkinson’s disease in mainland Han Chinese." (PMID 32984335, 2020).
prostate carcinoma (2 papers, 2018 to 2025). A carcinoma that arises from epithelial cells of the prostate gland. "We further identified increased promoter DMR methylation in prostate cancer correlating with decreased expression of mRNA and protein expression also on FBXO2, TGFB1I1, and TNS1." (PMID 29563510, 2018).
Alzheimer disease (1 paper, 2015). A progressive, neurodegenerative disease characterized by loss of function and death of nerve cells in several areas of the brain leading to loss of cognitive function such as memory and language. "In this work, we focused on knowledge cliffs next to some of the most-established interactions such as BACE1-APP and found four “potential new candidates”, namely TP53INP2, RTN4, F2RL3, and FBXO2, presumably new targets for Alzheimer’s disease as guided by the knowledge cliff concept." (PMID 26346705, 2015).
celiac disease (1 paper, 2022). An autoimmune genetic disorder with an unknown pattern of inheritance that primarily affects the digestive tract. "The most significantly up-regulated genes in celiac disease were TAP1, HLA-E, HCP5, STAT1, GBP1, STAT1, LOC100419583, and GBP4 and the down-regulated ones were IDS, PKIB, FBXO2, OXT, and ADI1." (PMID 36011206, 2022).
cognitive deficits (1 paper, 2023). "Finally, we investigated whether suppression of Fbxo2 in PFC of Tau mice was effective in rescuing cognitive deficits." (PMID 36609445, 2023). "Viral-based knockdown of Fbxo2 in PFC restores NMDAR-EPSC, leading to the amelioration of cognitive deficits, further confirming the important role of Smyd3-Fbxo2-NR1 pathway in AD pathophysiology." (PMID 36609445, 2023).
COVID-19 (1 paper, 2025). A disease caused by infection with severe acute respiratory syndrome coronavirus 2. "Subsequent validation by enzyme-linked immunosorbent assay (ELISA) in an expanded cohort—consisting of PASC patients, non-PASC COVID-19 convalescents, and pre-pandemic healthy controls—revealed two promising biomarkers: autoantibodies targeting PITX2 and FBXO2." (PMID 40004214, 2025).
diabetes (1 paper, 2013). "Line 9374 contains the proximal half of the Idd9.2 region, including Fbxo2 (encoding F-box protein 2), which has been implicated to have a role in diabetes progression." (PMID 23934554, 2013).
disc degeneration (1 paper, 2025). "In vivo, AAV9‐mediated FBXO2 delivery attenuated disc degeneration in rats by suppressing ferroptosis and restoring collagen II expression, whereas FBXO2 KO accelerated IVDD via LCN2‐dependent pathways." (PMID 40791152, 2025). "Complementary in vivo studies demonstrate that FBXO2 overexpression attenuates disc degeneration in rodent IVDD models, whereas FBXO2 deletion exacerbates disease progression through LCN2‐mediated ferroptotic pathways." (PMID 40791152, 2025).
glioblastoma (1 paper, 2024). The most malignant astrocytic tumor (WHO grade IV). "Three proteins have been identified as upregulated in recurrent glioblastoma and highly heterogeneous across patients: brain enriched myelin associated protein 1 (BCAS1), inverted formin 2 (INF2), and F-Box Protein 2 (FBXO2)." (PMID 39513861, 2024). "FBXO2-positive glioma cells were mostly associated with regions of the tumor with high immune reactivity and neurodevelopmental reactivation of the transcription program, while BCAS1 and INF2 were less specific and more widely diffused across the different regions of the glioblastoma." (PMID 39513861, 2024).
hearing loss (1 paper, 2018). "FBXO2 was originally described as a brain-specific F-box protein and has also been identified in cochlear cells; accordingly, FBXO2-knockout mice develop age-related hearing loss." (PMID 30052682, 2018).
Hepatic fibrosis (1 paper, 2025). The presence of excessive fibrous connective tissue in the liver. "Conversely, overexpression of MCL1 in the liver protected against the pro-apoptotic effects of FBXO2+ SMEV treatment, further confirming the role of MCL1 in FBXO2+ SMEV-mediated hepatic fibrosis." (PMID 40852599, 2025).
Hyperglycemia (1 paper, 2024). An increased concentration of glucose in the blood. "The ablation of FBXO2 in mice, therefore, mitigates T2D-related phenotypes, including hyperglycemia and glucose intolerance." (PMID 38212312, 2024).
Lysosomal disease (1 paper, 2020). "Furthermore, additional studies to probe the function of Fbxo2 will continue to advance our understanding of mechanisms involved in protein and organellar quality control pathways that likely contribute to the neuropathology in a diverse array of lysosomal diseases." (PMID 32931479, 2020).
oral cancers (1 paper, 2018). "Consistent with previous reports, EBV gB is retained in the ER and nuclear envelope and barely detectable on the plasma membrane (PM) in both NPC and oral cancer cell lines, while FBXO2 is a cytoplasmic protein." (PMID 30052682, 2018). "Besides, FBXO2 was highly expressed in oral cancer cell lines but absent in normal oral keratinocytes (NOK)." (PMID 30052682, 2018).
papillary thyroid carcinoma (1 paper, 2025).
rheumatoid arthritis (1 paper, 2025). A chronic, systemic autoimmune disorder characterized by inflammation in the synovial membranes and articular surfaces. "Notably, FBXO2 expression is increased in rheumatoid arthritis patients, coinciding with elevated levels of tripartite motif-containing 21 (TRIM21), also known as the SSA/Ro52 antigen." (PMID 40004214, 2025).
steatosis (1 paper, 2025). Increased lipid within the cytoplasm of cells. "When we silenced GRP94, the regulatory effects of AB23A on TG levels, cellular steatosis, ERS‐related proteins (p‐PERK/PERK, p‐eIF2α/eIF2α, ATF4), and ERAD‐related proteins (FBXO2, DERL, HSP90α) disappeared." (PMID 40051602, 2025).
tauopathy (1 paper, 2023). Neurodegenerative disorders involving deposition of abnormal tau protein isoforms (tau proteins) in neurons and glial cells in the brain. "Inhibiting Smyd3 or knockdown of Fbxo2 rescues synaptic and cognitive deficits in the mouse model of tauopathies." (PMID 36609445, 2023).
tumor (10 papers, 2020 to 2025). "The increased FBXO2 expression was associated with tumor stage, tumor grade, and histologic tumor type, and poor prognosis based on The Cancer Genome Atlas (TCGA) database." (PMID 32984335, 2020). "The results revealed that FBXO2 expression was significantly upregulated in tumor tissues compared to adjacent normal liver tissues." (PMID 41035649, 2025). "In line with these in vitro results, knockdown of FBXO2 significantly reduced the volume, size, and tumor of the subcutaneous tumors." (PMID 35525855, 2022). "Compared with the mice injected with RL95-2-NC cells, those injected with RL95-2-shFBXO2 cells displayed an attenuated rate of tumor growth while knockdown of both FBXO2 and FBN1 rescued this phenotype." (PMID 32984335, 2020). "We observed that knockout of FBXO2 significantly inhibited tumor growth, as depicted by measuring tumour volumes and weights." (PMID 32549792, 2020). "Collectively, these data indicate that FBXO2 functions as a tumor oncogene, and that it is essential for EC cell growth." (PMID 32984335, 2020). "Notably, these inhibitory effects were reversed upon USP49 silencing, indicating that USP49 mediates the tumor-suppressive effects of FBXO2 depletion." (PMID 41035649, 2025). "Beyond its role in tumor progression, we investigated whether FBXO2 contributes to sorafenib resistance in HCC." (PMID 41035649, 2025). "Furthermore, Western blotting, immunoprecipitation, in vivo ubiquitination assays, and cycloheximide chase analysis were conducted to investigate the molecular mechanisms through which FBXO2 contributes to tumor progression in HCC." (PMID 41035649, 2025). "Next, we showed the expression of SOX6 and FBXO2 was also positively correlated in some tumor types in the TCGA database, including OV, suggesting that SOX6 may be involved in the regulation of FBXO2 expression in OV." (PMID 35525855, 2022). "In summary, we have revealed a tumor-promoting role of FBXO2 and a connection with SOX6 in OV." (PMID 35525855, 2022). "FBXO2 KO cells were injected into nude mice to observe tumor growth in vivo." (PMID 32549792, 2020). "However, tumor weights were much higher with double-knockdown of FBXO2 and FBN1 compared with the RL95-2-shFBXO2 group." (PMID 32984335, 2020). "Interestingly, we found that FBXO2 was selectively highly expressed in OV among most tumor types from TCGA database, although its low expression was more common in some other tumors, suggesting that FBXO2 may play a unique role in OV." (PMID 35525855, 2022). "Functional assays demonstrated that FBXO2 promotes HCC cell proliferation, migration, and invasion in vitro, while its silencing exerts tumor-suppressive effects." (PMID 41035649, 2025). "Interestingly, we demonstrated that FBXO2 was down-regulated generally in BC, overexpression of FBXO2 stands for better RFS in Luminal B and HER2 types BRCA, while the expression was correlated with tumor stage in patients with BC." (PMID 33622332, 2021).
cancer (7 papers, 2018 to 2024). A tumor composed of atypical neoplastic, often pleomorphic cells that invade other tissues. "Furthermore, FBXO2 showed high expression in EC samples compared with para-carcinoma tissues, and was positively associated with muscular infiltration and Ki67 staining." (PMID 32984335, 2020). "As FBXO2 can recognize and degrade or even stabilize different glycosylated proteins, we cannot rule out that other substrates could also be involved in the cancer-promoting function of FBXO2." (PMID 35525855, 2022). "Gene Set Enrichment Analysis (GSEA) showed that a variety of cancer-promoting pathways including HEDGEHOG_ SIGNALING and WNT_BETA_CATENIN_ SIGNALING were significantly enriched in the FBXO2 high expression group from TCGA OV cancer database, suggesting a cancer-promoting role of FBXO2." (PMID 35525855, 2022). "Furthermore, both entities displayed a shared regulation of genes, including MYC, PHGDH, FBXO2 and BRDT, which promote cancer progression according to previous studies." (PMID 38725048, 2024). "Beyond its role in neuronal and cancer cell motility, the function of the CNA.42-binding protein, FBXO2, in human diseases, in general, and synovial disorders, in specific, is largely unknown." (PMID 36465908, 2022).
neurodegenerative disease (3 papers, 2018 to 2021). A disorder of the central nervous system characterized by gradual and progressive loss of neural tissue and neurologic function. "It is worth noting that FBXO2, another member of the FBA family, is associated with a number of neurodegenerative diseases by targeting various substrates for destruction." (PMID 33767133, 2021).
FBXO2 also shares sentences with these, for which no sentence is quoted: adenocarcinoma (1 paper); alcohol dependence (1); astrocytoma (1); Burkitt lymphoma (1); gastric tumors (1); glioma (1); Infertility (1); liver cancer (1); non-Hodgkin lymphoma (1); pancreatic cancer (1); Sepsis (1); serous ovarian tumor (1); squamous cell carcinoma (1); undifferentiated carcinoma (1).